CAP1 (cyclase associated actin cytoskeleton regulatory protein 1)
Diseases named in the same sentence as CAP1 in open-access papers (continued):
Sharing a sentence is not in itself a finding about the gene and the disease.
cancer (26 papers, 2009 to 2025). A tumor composed of atypical neoplastic, often pleomorphic cells that invade other tissues. "Gene CAP1 was associated with many cancer key genes, and GO analysis showed that protein CAP1 has a connection with actin." (PMID 34636991, 2022). "CAP1 is a cancer-associated protein, and according to UniProt and GO-Cellular component annotation, human CAP1 has an extensive expression." (PMID 34636991, 2022). "To date, CAP1 has been implicated largely in the invasiveness, of a growing list of human cancers, including breast, lung, pancreatic, and ovarian cancer, as well as neural glioma, hepatocellular carcinoma, and head and neck squamous cell carcinomas." (PMID 31151140, 2019). "Studies from our group and others have solidly established roles for CAP1 in regulating cell functions, the de-regulation of which underlies the major hallmarks of cancer, such as the actin cytoskeleton, cell adhesion, migration, and proliferation." (PMID 31151140, 2019). "The actin-regulating protein CAP1 is implicated in human cancers, while the role still remains elusive." (PMID 30894654, 2019). "Analyzing the five gene (CAP1) of mutations and CNAs by the cBioPortal tool with 91 different cancer studies." (PMID 28423713, 2017). "Further establishing the role and dissecting underlying mechanisms are imperative before targeting CAP1 can become a possibility for cancer treatment." (PMID 27173014, 2016). "The serine protease CAP1/Prss8 is crucial for skin barrier function, lung alveolar fluid clearance and has been unveiled as diagnostic marker for specific cancer types." (PMID 23405214, 2013). "Equally associated with cancer, matriptase seems to act as a tumor suppressor gene in vitro, an effect proposed to be mediated through CAP1/Prss8." (PMID 23405214, 2013). "CAP1 high transcription level associated with shorter OS in various cancers." (PMID 34636991, 2022). "This suggests the association between CAP1 gene expression in PBMCs and the development of cancer." (PMID 34290294, 2021). "Since cancer-related mutations in both CAP1 and CAP2 are more prevalent in the N-terminal part of the CAP isoforms, we compared the biochemical properties of the N-terminal region of both isoforms, which are recognized to bind F-actin and enhance cofilin-mediated filament disassembly." (PMID 31718088, 2019). "Moreover, the FAK/ERK axis appears to play a critical role in mediating CAP1 signals, to regulate cancer cell functions, the de-regulation of which underlie both morphological and proliferative transformations." (PMID 31151140, 2019). "The actin-regulating protein CAP1 is implicated in the invasiveness of human cancers." (PMID 27173014, 2016). "A number of scholars have started to investigate the association between CAP1 and cancer." (PMID 25652936, 2015). "Adenylate cyclase-associated protein 1 (CAP1) regulates both actin filaments and the Ras/cAMP pathway in yeast, and has been found play a role in cell motility and in the development of certain types of cancer." (PMID 25652936, 2015). "Some of the phosphoproteins identified in this study have been previously implicated in cancer malignancy such as Mcm2 and adenylyl cyclase associated protein (CAP1), while little information is available on some of the other potential targets including small acidic protein." (PMID 20661426, 2010). "A panel of Clathrin Heavy Chain (CLTC), Ezrin (EZR), Talin-1 (TLN1), Adenylyl cyclase-associated protein 1 (CAP1), and Moesin (MSN) positive exosomes demonstrated 0.94–0.99 accuracy against other cancers." (PMID 40363817, 2025). "Results showed that 108 datasets met the threshold, and among them, 20 analyses showed higher CAP1 mRNA level in cancer tissue when compared with normal tissue." (PMID 34636991, 2022). "TCGA database included in cBioPortal showed CAP1 gene had a high correlation with some key cancer-related genes which further confirmed the carcinogenesis role of CAP1." (PMID 34636991, 2022).
cancer (continued). "The overall survival (OS) between CAP1-high-expression and CAP1-low-expression mRNA level in different cancers was analyzed by Kaplan–Meier Plotter database." (PMID 34636991, 2022). "The mRNA level of CAP1 was overexpressed in most types of cancer tissues when compared with normal tissues." (PMID 34636991, 2022). "To investigate the expression levels of CAP1 in NSCLC patients and normal people, we analyzed CAP1 protein levels in human serum both from cancer patients and normal people." (PMID 34636991, 2022). "CAP1 has been found to be overexpressed in cancers, including pancreatic, lung, esophageal, liver, ovarian, breast, and glioma cancers." (PMID 32042970, 2020). "Mounting evidence suggests the involvement of CAP1 in a growing list of human cancers, with emerging evidence suggesting a more complex role that is dependent on the type (or even the subtype) of cancer." (PMID 31151140, 2019). "We found that the untransformed hTERT-HPNE cells expressed comparable levels of CAP1 to those in the cancer cell lines." (PMID 30894654, 2019). "All four cancer cell lines express abundant levels of CAP1 that is comparable to that in HeLa cells, which we previously reported to express abundant levels of both CAP1 and CAP212." (PMID 30894654, 2019). "The signaling kinases FAK and ERK likely play central roles, by mediating CAP1 signals to control the key cancer cell functions, including adhesion, invasiveness, and proliferation." (PMID 31151140, 2019). "Regardless, these mechanistic insights help to shape a more complete and in-depth picture concerning the roles of CAP1 in human cancers, such insights are also imperative before realizing that the translational potential of CAP1 can be possible." (PMID 31151140, 2019). "Whereas some earlier studies support this notion, lines of emerging evidence actually argues against such a clear-cut, stimulatory role for CAP1 in cancer invasiveness." (PMID 30894654, 2019). "Recent studies have unraveled a cell context-dependent role for CAP1 in mammalian cell motility and cancer cell invasiveness." (PMID 30894654, 2019). "Unsurprisingly, evidence is accumulating that implicates CAP1 in the invasiveness of a growing list of human cancers that include breast, pancreatic, liver, and lung cancer, and oral squamous cell carcinoma." (PMID 30894654, 2019). "It is possible that the increased pool of phosphorylated CAP1 in cancer cells reflects increased subcellular portions where CAP1 activity and local actin dynamics are reduced, which is a reasonable scenario to expect in a polarized cell." (PMID 30894654, 2019). "Our findings support that the role for CAP1 in cell adhesion is critical in the cell context-dependent roles for CAP1 in cancer cell invasiveness, which is highly relevant to cancer metastasis that accounts for the death of most cancer patients." (PMID 31151140, 2019). "Our results support that the activity of CAP1, regulated through phosphorylation at S308/S310 tandem site, is important for the protein function in regulating the invasiveness of cancer cells." (PMID 30894654, 2019). "Our results support that transient phosphorylation at the regulatory site is required for the CAP1 functions in cancer cells." (PMID 30894654, 2019). "Together, these findings support roles for CAP1 in both the morphological and proliferative transformation processes, which are the two most prominent hallmarks of cancer." (PMID 31151140, 2019). "Our study further establishes a required role for CAP1 in Matrigel invasion, which mimics tissue invasion in the body and is believed a better predictor of the metastatic potential of cancer cells." (PMID 30894654, 2019). "Consistent with the context-dependent roles in cell motility and cancer cell invasiveness, mounting evidence argues against a scenario where CAP1 is up-regulated in cancer such that it would universally stimulate cancer cell invasiveness." (PMID 31151140, 2019).
cancer (continued). "Based on these, the presumption was that up-regulated expression levels of CAP1 would stimulate cell motility and cancer cell invasiveness." (PMID 31151140, 2019). "CAP1 likely regulates cancer cell invasiveness through effects on both actin filament turnover and cell adhesion." (PMID 30894654, 2019). "Consistent with the enhanced stress fibers, depletion of CAP1 has been reported to reduce motility in a number of mammalian cell types, including cancer cells." (PMID 30894654, 2019). "The precise underlying mechanism through which CAP1 and CAP2 modulate cancer progression need to be further studied." (PMID 28423713, 2017). "The cBioPortal analysis program identified 12 types of human cancer with significant CNAs in the chosen genes’ signature (CAP1, CAP2, CFL1, CFL2, DSTN)." (PMID 28423713, 2017). "CAP1 regulates cancer mechanism through Tandem phosphorylation of S307 and S309 and association with cofilin and actin by GSK3 in HeLa cells." (PMID 28423713, 2017). "This is the first report for an inhibitory role for CAP1 in the invasiveness of human cancer cells, other than our previous report of such a role in HeLa cells." (PMID 27173014, 2016). "It is therefore critical to further establish the role for CAP1 in human cancers, including that across distinct sub-types of cancer." (PMID 27173014, 2016). "We next tested effect of CAP1 depletion on migration of cancer cells, by conducting both wound healing and Transwell migration assays." (PMID 27173014, 2016). "Phenotypes in cell proliferation and anchorage-independent growth in CAP1 knockdown cells consistently support a role for the protein in cancer cell proliferation, which we show is mediated by the ERK signaling." (PMID 27173014, 2016). "The cell spreading phenotypes also suggest that CAP1 knockdown in the metastatic cancer cells promoted the interaction of transmembrane receptors with fibronectin, a major component of ECM." (PMID 27173014, 2016). "Consistent with its cellular function as a key actin-regulating protein, mounting evidence supports involvement of CAP1 in the invasiveness of human cancers." (PMID 27173014, 2016). "Taken together, these results support that the ERK-GSK3/Snail/E-cadherin axis mediates the functions of CAP1 in cancer cell invasiveness and EMT." (PMID 27173014, 2016). "The invasiveness phenotypes in the CAP1 knockdown metastatic cancer cells were also supported by the phenotypes in lamellipodia, actin arcs and EMT." (PMID 27173014, 2016). "Therefore, given the important role of ABPs in cellular motility and the lack of data regarding the CTC architecture cytoskeleton, it is important to study the levels of CFL1, PFN1, and CAP1 in CTCs and systemic leukocytes in cancer patients." (PMID 37226274, 2022). "CAP1 mRNA transcription level between cancer and normal tissue was analyzed by Oncomine database." (PMID 34636991, 2022). "Five analyses showed lower CAP1 mRNA level in cancer tissue." (PMID 34636991, 2022). "Similar to CAP1, CAP2 has been implicated in cancer pathogenesis and particularly in invasiveness." (PMID 33072768, 2020). "However, knockdown of CAP1 in cancer cells led to enhanced stress fibers, reduced cell motility and invasion into Matrigel." (PMID 30894654, 2019). "Finally, PDGF (Platelet-Derived Growth Factor) induced dephosphorylation of CAP1 at S307/S309, suggesting that CAP1 likely links extracellular signals to cancer cell invasiveness." (PMID 30894654, 2019). "It remains to be better determined whether such roles of CAP1 are conserved across other cancer types." (PMID 31151140, 2019).
cancer (continued). "Finally, re-expression of WTCAP1 in the CAP1-knockdown cells also reduced E-Cadherin expression, further supporting that CAP1 is required for EMT in PANC-1 cancer cells." (PMID 30894654, 2019). "High invasiveness of cancer cells overexpressing CAP1 and CAP2 correlates with their roles in stimulating the turnover of actin filaments, which is essential for cell motility via promoted formation and turnover of pro-migratory structures such as filopodia and lamellipodia, leading to metastasis." (PMID 31718088, 2019). "The ubiquitously expressed isoform CAP1 drives mammalian cell migration, and accordingly, most studies on the involvement of CAP1 in human cancers have largely been based on the rationale that up-regulated CAP1 will stimulate cancer cell migration and invasiveness." (PMID 31151140, 2019). "Moreover, the invasion assays reveal that depletion of CAP1 also reduced the capability of PANC-1 cancer cells to penetrate and invade through Matrigel." (PMID 30894654, 2019). "Finally, since EMT (Epithelial-Mesenchymal Transition) is related to cancer cell invasiveness, we tested the potential effect of CAP1 knockdown on EMT." (PMID 30894654, 2019). "Moreover, we have unraveled cell context-dependent roles for CAP1 in cell motility and cancer cell invasiveness." (PMID 31151140, 2019). "However, evidence is accumulating against universal up-regulation of CAP1 in cancer cells, and suggests that CAP1 plays more complex roles in cell migration and cancer cell invasiveness, where the involvement of CAP1 in cell adhesion is likely to be critical." (PMID 31151140, 2019). "Considering the key function of CAP1 in facilitating cofilin-driven actin dynamics, it was speculated that up-regulation of CAP1 in cancer cells would stimulate cell invasiveness by speeding up the rate of actin filament turnover." (PMID 30894654, 2019). "Finally, our findings suggests a likely role for CAP1 in mediating extracellular growth factor signals, through phosphor-regulation at S308/S310, to control cancer cell invasiveness." (PMID 30894654, 2019). "However, the role for CAP1 in human cancers still remains elusive, with mounting evidence that suggests a role that is dependent on the type or even subtype of cancer, where potential activation of cell adhesion signaling likely plays a key role." (PMID 30894654, 2019). "While findings from some studies reported so far support this case, lines of evidence largely from our recent studies point to a more complex and profound role for CAP1 in the invasiveness of cancer cells, where the potential activation of cell adhesion signaling is believed to play a key role." (PMID 31151140, 2019). "These mechanistic insights may ultimately lead to therapeutic strategies targeting CAP1 or its peripheral cell signals in cancer treatment." (PMID 28423713, 2017). "Importantly, we further identify a role for CAP1 in proliferative transformation of cancer, which has largely been overlooked due to the cellular function of CAP1." (PMID 27173014, 2016). "Therefore, similar to the opposite effects of CAP1 depletion on the invasiveness cancer cells, knockdown of CAP1 also had opposite effects on the proliferation of metastatic and non-metastatic cells, consistent with the opposing alterations of ERK activity." (PMID 27173014, 2016). "Moreover, it is also novel that CAP1 actually fulfills cancer cell type-dependent functions, suggesting distinct roles for the protein in different subtypes of cancer within the same cancer." (PMID 27173014, 2016). "Moreover, we demonstrate functions for CAP1 in cancer cell proliferation and anchorage-independent growth, again in a cell context-dependent manner." (PMID 27173014, 2016). "Moreover, we further identify a role for CAP1 in regulating proliferative transformation of cancer cells, with ERK signaling playing pivotal roles in mediating both cell functions." (PMID 27173014, 2016).
cancer (continued). "Indeed, depletion of CAP1 in the metastatic cancer cells stimulated the activity of ERK while simultaneously inhibited the activity of GSK3; this fits perfectly with the regulatory mechanisms leading to up-regulated Snail." (PMID 27173014, 2016). "We further identify a role for CAP1 in the proliferative transformation of cancer cells." (PMID 27173014, 2016). "Thus, CAP1 likely plays cancer type-specific, and further, cell context-dependent roles in the invasiveness of human cancers." (PMID 27173014, 2016). "Similarly, RETN can facilitate EMT and sustain cancer stemness through CAP1-dependent mechanisms." (PMID 41383622, 2025). "However, the role for CAP1 in human cancers and in cell migration is still controversial, with mounting evidence suggesting a role that is dependent on the type or even subtype of cancer." (PMID 33072768, 2020). "Finally, the growth factor PDGF induced CAP1 dephosphorylation, suggesting CAP1 may mediate extracellular signals to control cancer cell invasiveness." (PMID 30894654, 2019). "Therefore, CAP1 may mediate upstream cell signals or physiological stimuli to control both the invasiveness and proliferation of cancer cells." (PMID 27173014, 2016). "The chronic inflammation inspired by TLR4 and CAP1 is involved in the malignancy process, as is the overexpression of TLR4 and CAP1 in the TME, contributing to the progression of cancer." (PMID 35875143, 2022). "Together, these results support a required role for CAP1 in the invasiveness and EMT in the PANC-1 cancer cells." (PMID 30894654, 2019). "Inhibition of GSK3 or re-expression of the phosphor mutants in the CAP1-knockdown PANC-1 cells, both disrupting transient phosphorylation of CAP1, consistently led to reduced cancer cell motility and invasion." (PMID 30894654, 2019). "Our findings from the CAP1-knockdown cells support that CAP1 is required for cancer cell motility and invasion, and results from GSK3 inhibition suggest that S308/S310 phosphorylation plays a key role in the CAP1 functions." (PMID 30894654, 2019). "Depletion of CAP1 in the metastatic MDA-MB-231 and BT-549 cancer cells stimulated the metastatic potential while it actually inhibited it in the non-metastatic MCF-7 cancer cells or in normal cells." (PMID 27173014, 2016). "We found that CAP1 depletion indeed reduced the expression of E-cadherin in BT-549 and MDA-MB-231 cancer cells, consistent with the elevated invasiveness caused by CAP1 depletion." (PMID 27173014, 2016). "Bright field imaging revealed remarkable morphological changes in CAP1-depleted MDA-MB-231 and BT-549 cancer cells." (PMID 27173014, 2016). "High expression of CAP1 can be related to poor prognosis in NSCLC patients and cancer metastasis." (PMID 34636991, 2022). "Results showed that CAP1 protein levels were significantly upregulated in the serum of NSCLC patients compared with that of normal people (p < 0.0001, Normal 812.8 ± 44.95, N = 62, Cancer 1624 ± 66.47, N = 78)." (PMID 34636991, 2022). "Moreover, the Resistin receptors CAP1 and TLR4 mediate the effects of Resistin on cancer cells through activation of STAT3 (signal transducer and activator of transcription 3) and are implicated in the resistance to chemotherapy." (PMID 33072768, 2020). "Secondly, available data to date do not support a universal up-regulation of CAP1 in cancer cells or tissues either." (PMID 30894654, 2019). "We also detected reduced FAK activity, without alterations in FAK expression levels, in the CAP1-knockdown PANC-1 pool cancer cells." (PMID 30894654, 2019). "It is also noted that treatment of cancer cells and control cells with 6-BIO consistently led to noticeable up-regulation of CAP1, through an unknown mechanism." (PMID 30894654, 2019). "Notably, attempts to silence CAP1 in CFPAC-1 and Mia PaCa-2 cancer cell lines, however, were unsuccessful." (PMID 30894654, 2019).